XK (X-linked Kx blood group antigen, Kell and VPS13A binding protein)
Description:
Recruits the lipid transfer protein VPS13A from lipid droplets to the endoplasmic reticulum (ER) membrane.
Synonyms: XKR1; Kx; X1k; NA; NAC
Tractability: Antibody: its Gene Ontology location is reachable by antibodies, with high confidence; UniProt predicts a signal peptide or a membrane-spanning region. PROTAC: ubiquitination databases record sites on it.
Gene: Protein-coding gene on chromosome X (37,685,791 to 37,732,130, forward strand). Ensembl gene ENSG00000047597.
Subcellular location: Endoplasmic reticulum membrane
Subcellular location (Human Protein Atlas): Mitochondria; Nucleoplasm; Vesicles
Pathways (Reactome):
Signal Transduction: Peptide ligand-binding receptors
Gene Ontology:
Molecular function: protein binding; protein-macromolecule adaptor activity
Cellular component: endoplasmic reticulum membrane; plasma membrane; membrane
Homologues: Orthologues: chimpanzee XK (100% identical), macaque XK (98% identical), rabbit XK (90% identical), dog XK (87% identical), guinea pig XK (87% identical), pig XK (85% identical), mouse Xk (82% identical), tropical clawed frog xk (68% identical), rat Xk (68% identical), zebrafish xk (62% identical). Paralogues in human: XKRX (40% identical), XKR3 (33% identical).
Diseases named in the same sentence as XK in open-access papers:
XK is named in the same sentence as 50 diseases in open-access papers, as found by Europe PMC text mining. Sharing a sentence is not in itself a finding about the gene and the disease. The quoted sentences say what the papers report.
McLeod syndrome (27 papers, 2011 to 2026). "VPS13A disease (formerly chorea-acanthocytosis; due to bi-allelic variants in VPS13A) and XK disease (formerly McLeod syndrome; due to variants of XK) are rare neurodegenerative diseases, classified together as the “neuroacanthocytosis syndromes”." (PMID 41522673, 2026). "Subsequent genetic testing revealed a pathogenic large deletion at Xp21.1-p11.3, encompassing multiple OMIM Morbid genes, including DMD, Cilia- and flagella-associated protein (CFAP47 infertility), and XK (McLeod syndrome)." (PMID 40745660, 2025). "McLeod syndrome is an X-linked recessive condition due to variants in the XK gene, including SNV and, in the 10% of cases, deletions from intragenic to multigene size, typically requiring MLPA to be detected." (PMID 40584247, 2025). "Genotyping identified a pathogenic variant of the XK gene c.268delT; p.(Tyr90fs) previously reported in two members of a family with neuroacanthocytosis due to the McLeod syndrome." (PMID 40590567, 2025). "We enquired PubMed searching for the following keywords: XK, McLeod syndrome, gene variants/changes, deletion, insertion, missense mutation; as well as cited manuscripts in the respective publications." (PMID 39233738, 2024). "Examples include granulomatous disease (OMIM 306400) due to CYBB mutation, Duchenne muscular dystrophy (OMIM 310200) due to DMD mutation, and McLeod syndrome (OMIM 300842) due to XK mutation." (PMID 39000307, 2024). "VPS13A disease (formerly chorea-acanthocytosis; due to bi-allelic mutations in VPS13A) and XK disease (formerly McLeod syndrome; due to mutations of XK) are rare neurodegenerative diseases, classified together as the “neuroacanthocytosis syndromes”." (PMID 37928888, 2023). "The XK gene variant, a highly specific diagnostic marker for McLeod syndrome, is the “gold standard” for the diagnosis of McLeod syndrome." (PMID 38343445, 2023). "Finding the interaction between VPS13A and XK is important because mutations in the VPS13A gene manifest clinically similarly to mutations in the XK gene causative of McLeod syndrome." (PMID 35563497, 2022). "McLeod syndrome is due instead to loss of function of XK, a member of a family of lipid scramblases whose function is to collapse the heterogeneity of the lipid composition of the two leaflets of the plasma membrane (PM)." (PMID 35994651, 2022). "McLeod syndrome is an X-linked recessive disorder, caused by mutations of the gene encoding for the McLeod protein XK." (PMID 34046249, 2021). "In four patients a core neuro-acanthocytosis syndrome was diagnosed: in two patients each from mutations in the VPS13A gene (confirming the diagnosis of VPS13A disease) and from mutations in the XK gene, associated with McLeod syndrome." (PMID 34046249, 2021). "The other main NA syndrome is McLeod syndrome with mutations in the XK gene, besides rare variants of NA such as Pantothenate kinase-associated neurodegeneration (PKAN), Huntington disease-like 2 or Abeta-/hypolipoproteinaemia syndromes besides others." (PMID 34046249, 2021). "Mutations in the VPS13A and XK genes cause chorea-acanthocytosis (ChAc) and McLeod syndrome, respectively." (PMID 34046249, 2021). "The VPS13A-XK interaction has significant disease implications as mutations in XK result in McLeod syndrome, a neuroacanthocytosis syndrome with similar phenotypes to VPS13A-associated chorea-acanthocytosis." (PMID 33809364, 2021). "Mutations in XK are highly correlated with McLeod syndrome with defects in the hematopoietic and neuromuscular systems." (PMID 34861826, 2021). "The diagnosis of McLeod syndrome was confirmed by the presence of a mutation of the XK gene on the X chromosome." (PMID 31775676, 2019). "McLeod syndrome is a rare X-linked multisystemic disease caused by mutations in the XK gene, which is thought to encode for a membrane transporter." (PMID 24529944, 2014).
McLeod syndrome (continued). "Despite the noted expression of XK in the cerebellum, McLeod syndrome has been associated previously with changes in the basal ganglia, a region not addressed in this study." (PMID 24179763, 2012). "The XK gene has been linked to McLeod syndrome, a syndrome with central nervous system, neuromuscular, and hematologic manifestations in males including movement, cognitive and psychiatric impairments." (PMID 24179763, 2012). "XK and ATP11C preserve membrane integrity: XK loss causes McLeod syndrome with acanthocytosis and reduced deformability that may impair merozoite entry, while ATP11C-mediated phosphatidylserine flipping prevents premature PS exposure and macrophage clearance." (PMID 41450567, 2025). "Also, alterations, most frequently deletions, in the XK gene have been associated with McLeod syndrome, including late onset myopathy and neuropathy." (PMID 41190063, 2025). "Deficiency in XK is known to cause McLeod syndrome, which shares many similarities with ChAc." (PMID 39514409, 2024). "McLeod syndrome, caused by mutations in XK gene, show an overlapping phenotype with ChAc." (PMID 37209156, 2023). "The symptoms of ChAc resemble those of McLeod syndrome caused by mutations in the XK gene." (PMID 34046249, 2021). "Here, we report 12 Italian patients with a molecular diagnosis of NA, nine belonging to five ChAC families (carrying bi-allelic variants of the VPS13A gene) and three belonging to the same family with McLeod syndrome (harboring a deletion of exon 1 of the X-linked XK gene)." (PMID 33652783, 2021). "The detection of mutations in the XK gene confirms a diagnosis of McLeod syndrome." (PMID 31775676, 2019). "XK protein is expressed in a number of tissues including CNS and blood cells, and mutations within XK protein are associated with McLeod syndrome, which is characterized as a multisystem disorder with numerous abnormalities in the neuromuscular and hematopoietic systems." (PMID 26191006, 2015). "We hereby were able to expand the mutational spectrum of XK mutations leading to McLeod syndrome." (PMID 24529944, 2014). "McLeod syndrome (MLS) is a rare X-linked neurohematologic disorder caused by loss-of-function mutations in the XK gene." (PMID 35451392, 2022). "McLeod syndrome (MLS) is an ultra-rare neurodegenerative X-linked disease caused by mutations in the XK gene, classified as one of the core neuroacanthocytosis syndromes." (PMID 34046249, 2021). "Rarely, CGD can be caused by a deletion in the X chromosome with larger deletions involving neighboring genes, including DMD (Duchenne muscular dystrophy) and XK (McLeod Syndrome)." (PMID 40745660, 2025). "This group encompasses autosomal recessive chorea-neuroacanthocytosis (ChAc) and X-linked McLeod syndrome (MLS) with mutations in the VPS13A gene and the XK gene, respectively." (PMID 39183347, 2024). "Chorea-acanthocytosis and McLeod syndrome are due to mutations in VPS13A and XK, respectively, but share similar clinical manifestations: movement disorders due to degeneration of the caudate nucleus and acanthocytes, i.e. spiculated red blood cells (RBCs)." (PMID 37928888, 2023). "The NAS spectrum includes the neurodegenerative disorders chorea-acanthocytosis (VPS13A disease) and McLeod syndrome (XK disease) caused by gene mutations in VPS13A and XK, respectively." (PMID 37928888, 2023). "Chorea-acanthocytosis and McLeod syndrome, due to mutations in VPS13A and XK, respectively, share similar manifestations: jerking movements due to degeneration of the caudate nucleus and star-shaped erythrocytes." (PMID 35994651, 2022). "Chorea-acanthocytosis (ChAc) and McLeod syndrome are diseases with shared clinical manifestations caused by mutations in VPS13A and XK, respectively." (PMID 35994651, 2022). "Much of what we currently know about the gene derives from knowledge on the related XK-gene and XK-protein, a deletion of which leads to McLeod syndrome." (PMID 24179763, 2012).
McLeod syndrome (continued). "We ruled out the possibility that our cases were McLeod syndrome, as our exome sequencing did not identify any mutation in the XK gene." (PMID 37209156, 2023). "WES revealed a stop-gain mutation (c.799C > T; p.R267X) in the VPS13A gene while no mutation was found in the XK gene, confirming the patient as a case of ChAc and overruling the possibility of McLeod syndrome." (PMID 37209156, 2023). "Cooperation between VPS13A and XK, which has recently been confirmed by in vitro studies to have scramblase activity, would represent another example of such a partnership, providing clues to mechanisms of disease in chorea-acanthocytosis and McLeod syndrome." (PMID 35994651, 2022). "Together with the X-linked McLeod syndrome (MLS, OMIM #300842), due to loss-of-function (LOF) variants of the XK gene (*314850), ChAc accounts for the “core” neuroacanthocytosis (NA) syndromes, defined by the combination of RBC acanthocytosis and basal ganglia-related neurological disorders." (PMID 33652783, 2021). "The later age of onset for McLeod syndrome may be due to functional redundancy between XK and its 7 homologs." (PMID 33809364, 2021). "Direct interactions between VPS13A and XK proteins may explain some of the common features between ChAc and McLeod syndrome." (PMID 34046249, 2021). "We hereby present a patient with a novel XK frameshift mutation associated with a McLeod syndrome without signs of chronic granulomatous disease (CGD)." (PMID 24529944, 2014). "When XK is absent on RBC membranes, McLeod syndrome develops." (PMID 22111908, 2011).
chorea-acanthocytosis (7 papers, 2012 to 2026). Chorea-acanthocytosis (ChAc) is a form of neuroacanthocytosis and is characterized clinically by a Huntington disease-like phenotype with progressive neurological symptoms including movement disorders, psychiatric manifestations and cognitive disturbances. "Mutations in VPS13A and XK are associated with chorea-acanthocytosis (ChAc) and Mcleod (MLS) syndromes respectively." (PMID 41522673, 2026). "The core neuroacanthocytosis syndromes, i.e., chorea-acanthocytosis/VPS13A disease (ChAc) and McLeod syndrome/XK disease (MLS), are respectively due to mutations in VPS13A and XK genes and share similar manifestations including the formation of acanthocytes." (PMID 40213144, 2025). "Chorea-acanthocytosis (ChAc) relates to mutations in VPS13A, McLeod Syndrome (MLS) has mutations in XK, Huntington’s Disease-like 2 (HDL2) in JPH3, and panthotenate kinase-associated neurodegeneration (PKAN) in PANK2." (PMID 24098554, 2013). "Genetic studies in the two core NA disorders, McLeod syndrome (MLS) and chorea-acanthocytosis (ChAc), have resulted in the identification of mutations on (i) the XK gene (X-chromosome) encoding for Xk protein in MLS and (ii) the VPS13A gene (chromosome 9), encoding for chorein in ChAc." (PMID 22355334, 2012).
acanthocytosis (4 papers, 2014 to 2025). "Red blood cell acanthocytosis in McLeod syndrome is associated with absent expression of the Kx antigen and reduced expression of the Kell antigen on the surface membranes of erythrocytes, which are caused by truncation or no expression of XK protein." (PMID 31775676, 2019).
Duchenne muscular dystrophy (4 papers, 2023 to 2025). Duchenne muscular dystrophy (DMD) is a neuromuscular disease characterized by rapidly progressive muscle weakness and wasting due to degeneration of skeletal, smooth and cardiac muscle. "CMA with adequate resolution to identify the deletion boundary can define whether there is loss of implicated genes contiguous to CYBB in these cases, e.g., XK (Kx blood group antigen), RPGR (retinitis pigmentosa), DMD (Duchenne muscular dystrophy) and OTC (ornithine transcarbamoylase)." (PMID 39124702, 2024). "When XK gene segment deletions are excessive, they may involve contiguous XK genes, such as the CYBB and RPGR genes, which could result in “Xp21 DNA microdeletion syndrome”, including XLRP, chronic granulomatous disease, Duchenne muscular dystrophy, and ornithine transcarbamylase deficiency (OTC)." (PMID 38343445, 2023).
Chorea (3 papers, 2014 to 2024). Chorea (Greek for 'dance') refers to widespread arrhythmic involuntary movements of a forcible, jerky and restless fashion. "Very common are weakened Kell antigen (100%), changes in muscle biopsy (100%), genetic alterations in XK (100%), elevated creatine kinase (97%), acanthocytes (96%), MRI changes (95%), chorea (84%) and hyporeflexia (82%)." (PMID 39183347, 2024).
chronic granulomatous disease (3 papers, 2014 to 2024). Chronic granulomatous disease (CGD) is a rare primary immunodeficiency, mainly affecting phagocytes, which is characterized by an increased susceptibility to severe and recurrent bacterial and fungal infections, along with the development of granulomas. "Larger deletions in the XK gene may also involve chronic granulomatous disease, dystrophinopathy, retinitis pigmentosa and ornithine transcarbamylase deficiency (Peikert, Hermann, and Danek 2022)." (PMID 39324427, 2024).
cardiomyopathy (2 papers, 2023). A disease of the heart muscle or myocardium proper. "McLeod's syndrome (MLS) is an X-linked disorder caused by mutations in the XK gene with neurological manifestations as well as cardiomyopathy." (PMID 37720304, 2023).
neuropathy (2 papers, 2024 to 2025). A disorder affecting the nervous system that manifests with pain, tingling, numbness, and/or muscle weakness. "However, thorough work-up revealed longer-standing changes including neuropathy, muscle atrophy with fatty involution and raised CK, indicating longer-standing neuropathy and myopathy most likely due to the underlying genetic defect in the XK gene." (PMID 39233738, 2024). "Clinical findings associated with XK variants comprise a multisystemic spectrum disorder including acanthocytosis, haemolysis, anaemia, spleno- and hepatomegaly, cardiomyopathy, myopathy, neuropathy, dystonia, choreatic movement disorders as well as neuropsychiatric disorders and cognitive decline." (PMID 39233738, 2024). "Here, we report a novel deletion in XK in a patient with elevated creatine kinase, signs of myopathy and neuropathy as well as raised levels of activated T-lymphocytes in CSF." (PMID 39233738, 2024).
graft versus host disease (1 paper, 2021). An immune system disorder that occurs after allogeneic hematopoietic stem cell transplant and is a reaction of donor immune cells against host tissues. "Genes in the high-expression cohorts of FECH, GYPA, RPIA, and XK were highly enriched in ribosome, graft versus host disease, primary immunodeficiency, and B cell receptor signaling pathways, respectively." (PMID 34861826, 2021).
Huntington’s chorea (1 paper, 2021). "The protein XK, which has been implicated in non-Huntington’s chorea, distributes to light fractions 1–5 and to the center of the gradient (fractions 7–9)." (PMID 33815086, 2021).
Lipid storage disease (1 paper, 2025). "The discovery of XK's function as a lipid scramblase further raised the question about the presence of signs of lipid storage disease." (PMID 40898647, 2025).
malaria (1 paper, 2025). Malaria is a serious and sometimes fatal disease caused by a parasite that commonly infects a certain type of mosquito which feeds on humans. "Thus, XK is an indirect but functionally relevant modulator of malaria susceptibility." (PMID 41450567, 2025). "No population data link XK variants to malaria, yet CRISPR KEL-null erythrocytes show 60% invasion reduction." (PMID 41450567, 2025).
schizophrenia (1 paper, 2015). A major psychotic disorder characterized by abnormalities in the perception or expression of reality. "The marginally preserved turquoise module had 13 and 16 hub genes in CTS and SZP, respectively, with an overlap of only eight hubs, from which three were previously associated with schizophrenia: ADARB1, PNOC and XK." (PMID 25981335, 2015).
cancer (3 papers, 2015 to 2025). A tumor composed of atypical neoplastic, often pleomorphic cells that invade other tissues. "The downregulation of their expression is associated with better prognosis in several cancers, such as XK in ACC, CNNM4 in READ, KEL in CESC, CNNM3 in KIRC, as well as CNNM2 in LGG and KIRC." (PMID 41174507, 2025). "We also identified alterations in genes involved in various critical biological processes: MDC1, associated with DNA damage response and drug resistance in MM; DAXX, involved in chromatin regulation; GPNMB, linked to immunosuppression in cancer; and XK, which plays a role in hematopoiesis." (PMID 39769182, 2024). "The mutation rates of different MHGs varied widely across cancer tissues, with ANK3 having the highest mutation rate (47%), followed by KEL (18%), TRPM7 (16%), KCNA1 (13%), CNNM2 (9%), CNNM1 (9%), TFAP2B (9%), CNNM4 (9%), XK (7%), and EDN3 (5%)." (PMID 41174507, 2025).
genetic disorder (1 paper, 2024). "XK disease is a genetic disorder caused by mutations in the XK gene on the X chromosome that result in the loss or dysfunction of the encoded protein." (PMID 39119561, 2024).
neurodegenerative disease (1 paper, 2026). A disorder of the central nervous system characterized by gradual and progressive loss of neural tissue and neurologic function. "Furthermore, we present first quantitative measurements of XK and VPS13A protein levels in a healthy control cohort, in the related disorders and other neurodegenerative diseases." (PMID 41522673, 2026).
tumor (1 paper, 2023). "Moreover, XK-81 increased CD8+ T cells and NK cells numbers and regulated M1/M2 macrophage ratio in tumor tissues, indicating XK-81’s immunotherapeutic effect." (PMID 37513222, 2023).
XK also shares sentences with these, for which no sentence is quoted: influenza (38 papers); infection (15); avian influenza (10); neuroacanthocytosis syndromes (4); viral infection (4); myopathy (3); Co-infection (2); peripheral neuropathy (2); retinitis pigmentosa (2); swine influenza (2); acute respiratory distress syndrome (1); axonal neuropathy (1); Batten disease (1); breast tumor (1); Charcot-Marie-Tooth disease type 1A (1); Coffin-Siris syndrome (1); cognitive decline (1); connective tissue disorder (1); COVID-19 (1); dystrophinopathy (1); glioma (1); Hyporeflexia (1); Infertility (1); Loeys-Dietz syndrome (1); ornithine transcarbamylase deficiency (1); Parkinson disease (1); primary ciliary dyskinesia (1); primary immunodeficiency (1); pulmonary diseases (1); respiratory infections (1).
A further 3 diseases each share a sentence with XK in 1 paper.